TEP1 (telomerase associated protein 1)
Diseases named in the same sentence as TEP1 in open-access papers (continued):
Sharing a sentence is not in itself a finding about the gene and the disease.
parasite infection (8 papers, 2012 to 2025). "This included the gene encoding tep6, a thioester-containing protein in the same family as tep1, which is implicated in An. gambiae resistance to parasite infection." (PMID 39294791, 2024). "Next, we investigated the underlying mechanism of enhanced TEP1 expression in hemocytes induced by CSPmut parasite infection." (PMID 35680915, 2022). "When both TOR and TEP1 were knocked down, mosquitoes displayed increasing susceptibility to parasite infection compared to dsTOR mosquitoes, but these mosquitoes still had significantly fewer oocysts than dsTEP1 ones did." (PMID 33626094, 2021). "This is significant because the different TEP1 alleles are also known to govern mosquito susceptibility to parasite infection: mosquitoes expressing the R1 TEP1 allele are highly resistant to parasite infection, whereas those homozygous for the other versions of the gene are susceptible." (PMID 26394127, 2015). "Previous research showed the relevance of the IMD pathway components and regulated effector TEP1, in parasite infection intensity-dependent defense." (PMID 40170182, 2025). "Its microbiota regulates the expression of a thioester-containing protein 1 (TEP1) following parasite infection." (PMID 29554951, 2018). "tep1 inactivation prevents microbiota from protecting the mosquito against parasitic infections." (PMID 29554951, 2018). "In Anopheles gambiae, activation of Toll signaling mediated by dsCactus treatment resulted in increased basal expression of TEP1 and LRIM1, immune genes that inhibit development of Plasmodium, resulting in a lower burden of parasite infection." (PMID 36522779, 2022). "Finally, we established the relevance of the Imd pathway components and regulated effectors TEP1, APL1, and LRIM1 in parasite infection intensity-dependent defense, thereby shedding light on the relevance of laboratory versus natural infection intensity models." (PMID 22685401, 2012).
glioma (6 papers, 2020 to 2025). A benign or malignant brain and spinal cord tumor that arises from glial cells (astrocytes, oligodendrocytes, ependymal cells). "Collectively, these data suggest that Tep1 is required in the growth and differentiation of NSCs, and loss of Tep1 in glioma leads to reduction of glioma growth by reducing neuroblast number." (PMID 32457905, 2020). "Further, downregulation of Tep1 caused a reduction in Yki activity and reduced glioma growth." (PMID 32457905, 2020). "These revealed negligible changes in NRF2 mRNA levels in glioma cell lines following TEP1 knockdown or overexpression." (PMID 40583858, 2025). "By combining bioinformatics prediction with LC–MS/MS analysis, we identified TEP1, a protein with an unreported role in gliomas, as a downstream functional protein of circMAN1A2‐induced ferroptosis in GSCs." (PMID 40583858, 2025). "In a Drosophila glioma model, the downregulation of TEP1 reduced the activity of Yki and curtailed the growth of glioma." (PMID 37818043, 2023). "In a Drosophila glioma model, it was also shown that TEP1 (Drosophila ortholog of human CD109) regulates the Drosophila Yki pathway (ortholog to Yap/Taz)." (PMID 33738281, 2021). "We tested if Tep1 acts through Yki to affect glioma growth, and if in normal cells Tep1 affects neuroblast number and proliferation." (PMID 32457905, 2020). "We further show that Tep1 downregulation specifically restricts this ectopic progression thereby restricting neuroblasts to the CB and reducing glioma growth." (PMID 32457905, 2020). "Further, reduction in the glioma size by downregulation of Tep1 likely occurs through downregulation of cell proliferation." (PMID 32457905, 2020). "Our study also demonstrates that the Tep-Yki interaction plays an important role in glioma growth due to the effect of Tep1 on Yki-mediated neuroblast proliferation." (PMID 32457905, 2020). "Our data suggests that Tep1 affects Yki mediated stem cell renewal in glioma, as reduction of Tep significantly decreases the number of neuroblasts in glioma." (PMID 32457905, 2020). "Recently, CD109/ (Tep1 in Drosophila) was shown to be a novel upstream regulator of YAP/TAZ during glioma growth." (PMID 32457905, 2020). "Overall, we show a mechanism for glioma growth that depends on Yki and show that Tep1 acts upstream of Yki in this system." (PMID 32457905, 2020). "When Tep1 is downregulated in glioma (repoGal4>UAS-PtenRNAi; UAS-RasV12; UAS-GFP/UAS-Tep1RNAi), both Mira (C”) and Pros (C”’) expression domains are restricted back to the central brain region." (PMID 32457905, 2020). "We further show that the recently identified Yki modifier, Tep1 (Drosophila ortholog of CD109) is a modifier of glioma phenotype due to its effect on NSC number." (PMID 32457905, 2020). "Exploring the molecular function of TEP1 in gliomas, especially in GSCs, could provide novel avenues for glioma therapy." (PMID 40583858, 2025). "Overexpression of circMAN1A2 inhibited glioma progression, an effect that could be blocked by the overexpression of TEP1, as evidenced by enlarged necrotic areas within the tumor observed through HE staining." (PMID 40583858, 2025). "Thus, we identify Tep1-Yki interaction in the larval CNS that plays a key role in glioma growth and progression." (PMID 32457905, 2020). "The reduction in the neuroblast number may be attributed to the effects of Tep1 downregulation, which compromises Yki mediated stem cell function in glioma thereby identifying a new upstream regulator of Yki in the larval CNS." (PMID 32457905, 2020). "So next, we tested if Tep1 was involved in growth or differentiation of NSCs in our glioma model." (PMID 32457905, 2020). "We previously showed that loss of the Drosophila homolog of CD109, Thioester containing protein 1 (Tep1) in glioma cells (repo-Gal4> UAS-GFP, UAS-PtenRNAi, UAS-RasV12, UAS-Tep1RNAi) substantially reduced Yki levels and activity, and attenuated gliomagenesis in-vivo." (PMID 32457905, 2020).
glioma (continued). "Given the lack of tools for Tep1 overexpression, and our previous data suggesting a downstream role for Yki, we compared the effects of loss of Tep1 or Yki or both in the glioma model." (PMID 32457905, 2020). "However, the role of TEP1 in the biological progression of gliomas remains unexplored." (PMID 40583858, 2025). "The similarity of glioma reduction phenotypes of downregulation of Tep1 and downregulation of Yki or both suggests that Tep1 may act through Yki and the Hippo pathway to regulate NSC number, or that Tep1and Yki synergistically regulate NSC number in Drosophila larval brain." (PMID 32457905, 2020). "To understand if the Tep1-dependent effects occur through Yki, we downregulated Yki (repoGal4>UAS-PtenRNAi; UAS-RasV12; UAS-GFP/UAS-YkiRNAi) in the glioma model." (PMID 32457905, 2020).
breast carcinoma (5 papers, 2007 to 2023). "Previous studies have provided evidence for the relation of mutations in TEP1 and breast cancer." (PMID 33324444, 2020). "In a population-based study of 1995 breast cancer cases and 2296 controls from Poland, 24 SNPs representing common variation in POT1, TEP1, TERF1, TERF2 and TERT were genotyped." (PMID 17848914, 2007). "Six variants had no additional breast-cancer-affected carriers identified in the pedigrees they were originally found in (in genes KIF15, TMEM192, MUC5AC, TEP1, ZFX, and TNN)." (PMID 38136396, 2023).
prostate carcinoma (5 papers, 2017 to 2023). A carcinoma that arises from epithelial cells of the prostate gland. "Gu and co-authors found that TEP1 rs1713418 AG + AA genotypes were associated with 1.3-fold increased odds of prostate cancer in individuals younger than 69 years compared with the AA genotype (OR: 1.32, (95% CI: 1.02–1.70), p = 0.034)." (PMID 37762804, 2023). "The researchers also found that TEP1 rs1760904 AG and AG/AA genotypes were statistically significantly associated with a reduced risk of prostate cancer compared to the GG genotype (p = 0.003; p = 0.005, respectively)." (PMID 35892421, 2022). "Gu and co-authors found that the distribution of TEP1 rs1760904 polymorphism genotypes between the control and prostate cancer groups was statistically significant (p = 0.012)." (PMID 35892421, 2022). "Moreover, a significant interaction was found between the TEP1 rs1713418 polymorphism and age, with AG/GG genotypes associated with a 32% increased risk of prostate cancer in younger subjects and 29% reduced risk in older subjects." (PMID 35892421, 2022).
bladder cancer (4 papers, 2012 to 2023). "Future studies are needed to determine how this TEP1 SNP affects TEP1 function, telomerase activity, and bladder cancer risk." (PMID 22363464, 2012). "The initial split was at rs2228041 of TEP1, the most significant SNP out of those evaluated for bladder cancer risk." (PMID 22363464, 2012). "TEP1 SNP (rs1760897) has recently been associated with an increased risk of bladder cancer." (PMID 35892421, 2022). "A SNP (rs1760897) in TEP1 has recently been associated with an increased risk of bladder cancer." (PMID 22363464, 2012). "Previous studies have found that single-nucleotide polymorphisms (SNPs) in telomere pathway genes associated with altered cancer risk; for example, a recent study found variants of telomerase-associated protein (TEP1) associated with increased bladder cancer risk." (PMID 22363464, 2012). "In addition, in our study, we found 7 TEP1 SNPs associated with increased bladder cancer risk." (PMID 22363464, 2012). "All of the SNPs in TEP1 were associated with increased risk, and all SNPs except one in PINX1 were associated with reduced risk of bladder cancer." (PMID 22363464, 2012). "In addition to TEP1, we found high significance in a SNP on the PINX1 gene and lower bladder cancer risk." (PMID 22363464, 2012). "Our haplotype analysis also supports the role of TEP1 in bladder cancer etiology." (PMID 22363464, 2012).
immune deficiency (4 papers, 2013 to 2025). "Further analysis showed that AsTEP15 mainly negatively affects the TEP1 and immune deficiency (IMD) pathway, thereby inhibiting melanization." (PMID 40170182, 2025). "APL1, LRIM1, and TEP1 are transcriptionally controlled by Rel2 and Rel1, NF-κB transcription factors that function downstream of Toll and Immune Deficiency (IMD) signaling, respectively." (PMID 30496310, 2018).
liver fibrosis (4 papers, 2020 to 2023). "Telomerase-associated protein 1 (TEP1), a component of telomerase and target of hsa-miR-660-3p, plays a key role in the development of liver fibrosis and cirrhosis." (PMID 34440714, 2021). "Considering that hsa-miR-660-3p inhibitor and TEP1 overexpression reappear well the phenotypes of hsa_circ_0004018 downregulation, we highlight the hsa_circ_0004018/hsa-miR-660-3p/TEP1 axis in the proliferation and activation of HSCs and liver fibrosis." (PMID 32584784, 2020). "TEP1 is one of the telomerase components, which assists in telomere maintenance, and previous studies have shown that telomeres in hepatocytes or immune cells may be involved in liver fibrosis." (PMID 37371520, 2023). "In short, the hsa_circ_0004018/hsa-miR-660-3p/TEP1 axis is related to HSC activation and proliferation, which is the potential novel therapeutic strategy for liver fibrosis." (PMID 37371520, 2023). "However, the function of TEP1 in the HSCs and its role in liver fibrosis remained unknown before." (PMID 32584784, 2020).
viral infection (4 papers, 2015 to 2024). "It has been shown that hemocytes express humoral factors such as TEP1, PPO, and certain antimicrobial peptides that are known to restrict viral infections." (PMID 36298644, 2022). "TEP1, in cooperation with other proteins, can regulate mechanisms such as melanization, AMP expression, and phagocytosis, which can have an impact on viral infection." (PMID 36298644, 2022). "In response to the WSSV infection, the expressions of TEP1 and TEP2 were significantly upregulated, indicating that the two genes played very important roles in the virus infection." (PMID 26671453, 2015). "The silencing of TEP1 or TEP2 led to an increase of WSSV copies in shrimp, showing TEP1 and TEP2 were involved in the shrimp immune response against virus infection." (PMID 26671453, 2015). "It was found that when TEP1 was over-expressed, the viral load was reduced; however, over-expression of TEP3 did not lead to a reduction of viral load, thereby confirming the role of TEP1 in regulating viral infection." (PMID 30096752, 2018). "RNAi-mediated overexpression and silencing of TEP1 and TEP3 revealed that the viral load was reduced when TEP1 was overexpressed, but TEP3 overexpression did not lead to a reduction in viral load, further illustrating the role of TEP1 in regulating viral infection." (PMID 38368353, 2024).
lung carcinoma (3 papers, 2019 to 2022). "Alterations in TEP1 (Telomerase associated protein 1) were confirmed to cause several types of tumors in humans, including brain, breast, prostate and lung cancers." (PMID 34107880, 2021).
diffuse malignant peritoneal mesothelioma (2 papers, 2017 to 2022).
fungal infection (2 papers, 2012 to 2022). "However, this possibility was excluded because fungal infection triggered a similar survival pattern in TEP1 kd mosquitoes pre-treated with a cocktail of antibiotics." (PMID 23166497, 2012).
glioblastoma (2 papers, 2022). The most malignant astrocytic tumor (WHO grade IV). "We identified an increase in expression of TEP1, TERF1, and TERF2IP in glioblastoma and astrocytoma cell lines compared to HDFa and NHA control cell lines." (PMID 36142793, 2022).
male infertility (2 papers, 2015 to 2021). The inability of the male to effect fertilization of an ovum after a specified period of unprotected intercourse. "The TERT rs2736100 was inversely associated with male infertility risk, whereas TEP1 rs1713449 was positively associated with risk of male infertility, constituting that STLs could indeed pose as a risk factor for male infertility." (PMID 34842724, 2021).
ovarian carcinoma (2 papers, 2017 to 2023). A malignant neoplasm originating from the surface ovarian epithelium. "Eleven SNPs from two genes showed significant associations with overall ovarian cancer risk, 10 of which were located on TEP1 gene." (PMID 28233473, 2017). "The most significant SNP was TEP1: rs2228026 with participants carrying at least one variant C allele exhibiting a 3.28‐fold (95% CI: 1.72–6.29; P < 0.001, Q = 0.028) increased ovarian cancer risk." (PMID 28233473, 2017). "The most significant SNP was TEP1: rs2228026 with participants carrying at least one variant allele exhibiting a 3.28‐fold (95% CI: 1.72‐6.29; P < 0.001, Q = 0.028) increased ovarian cancer risk, which remained significant after multiple testing adjusting." (PMID 28233473, 2017). "Seven SNPs from two genes (TEP1 and TNKS) showed significant associations with ovarian cancer survival (P < 0.05, Q < 0.10)." (PMID 28233473, 2017). "Among the genotyped 145 SNPs, 11 SNPs from two genes (TEP1 and TERT) showed significant associations with overall risk of ovarian cancer (P < 0.05 and Q < 0.10)." (PMID 28233473, 2017).
airway allergy (1 paper, 2024). "The results suggest that the activities of TL/TERT/TEP1 in Tregs are associated with the pathogenesis of airway allergy." (PMID 38205251, 2024).
autism (1 paper, 2025). Persistent deficits in social interaction and communication and interaction as well as a markedly restricted repertoire of activity and interest as well as repetitive patterns of behavior. "In VPA females’ model of autism, nooclerin exerted the most pronounced influence on alterations in the transcriptional activities of the tnks genes, telomerase (Tep1, Dkc1) and the shelterin complex (Terf2ip, Pot1a, Tinf2, Tpp1, Trf1 - 2) in the hippocampus." (PMID 40272729, 2025).
cardiac hypertrophy (1 paper, 2024). "PARP2 has been associated with cardiac hypertrophy, TEP1 has been associated with myocardial infarction (MI) and ischemic stroke, and TTC5 has been associated with cardiovascular disease." (PMID 38473795, 2024).
cerebral palsy (1 paper, 2023). A group of disorders affecting the development of movement and posture, often accompanied by disturbances of sensation, perception, cognition, and behavior. "Mutations in TEP1 were thought to be responsible for the development of cerebral palsy." (PMID 37818043, 2023).
escherichia coli infection (1 paper, 2017). Infection with the organism Escherichia Coli. "Recently, CLIPA2 was shown to regulate melanization indirectly by controlling TEP1 activity during systemic infections; CLIPA2 kd enhanced TEP1 activity, leading to an exaggerated PO activity in the hemolymph following Escherichia coli infections." (PMID 28928218, 2017).
Flavivirus Infections (1 paper, 2023). Infections with viruses of the genus FLAVIVIRUS, family FLAVIVIRIDAE. "Additionally, recent studies have reported that AAEL012267, known previously as Ae. aegypti TEP1 or Ae. aegypti MCR, has a potential role in combating flavivirus infection of Ae. aegypti." (PMID 37277542, 2023).
leukemia (1 paper, 2013). A malignant (clonal) hematologic disorder, involving hematopoietic stem cells and characterized by the presence of primitive or atypical myeloid or lymphoid cells in the bone marrow and the blood. "We found that CXCL1, CXCL6, TEP1, IL8, CCL2 and PTGS2 genes were the most up-regulated genes in BMSCs co-cultured in the direct contact with leukemia cells." (PMID 24304929, 2013).
Pituitary Adenomas (1 paper, 2022). "TEP1, TERC, and TERT genes single nucleotide polymorphisms were analyzed to evaluate the associations with pituitary adenoma activity, invasiveness, and relapse." (PMID 35892421, 2022). "Also, we aimed to investigate the relationship between serum TEP1 levels and pituitary adenoma development." (PMID 35892421, 2022). "Thus, this study aimed to determine the relationship between the molecular markers of telomerase complex (TERC rs12696304, rs35073794, TEP1 rs1713418, rs1760904, and TERT rs2736098, rs401681) and the relative leukocyte telomeres length with the development of pituitary adenoma." (PMID 35892421, 2022).
ulcerative colitis (1 paper, 2023). An inflammatory bowel disease involving the mucosal surface of the large intestine and rectum. "Sipos and co-authors found that TEP1 expression increases in ulcerative colitis during mild inflammation." (PMID 37762804, 2023).